MUC5AC (mucin 5AC, oligomeric mucus/gel-forming)
Diseases named in the same sentence as MUC5AC in open-access papers (continued):
Sharing a sentence is not in itself a finding about the gene and the disease.
pancreatic cancer (continued). "Aberrant glycosylation of MUC5AC has also been studied in pancreatic cancer (with various techniques including immunohistochemistry, mass spectrometry, and serum ELISA) where certain variants of MUC5AC are associated with malignant transformation and promotion of carcinogenesis." (PMID 36672382, 2023). "In summary, the results of this study show that MUC5AC is an excellent biomarker fordiagnosing pancreatic cancers and may facilitate this difficult diagnosis on smallbiopsies." (PMID 35764407, 2022). "Since IL-8 produced by cancer cells induces neutrophil migration, it has been demonstrated that MUC5AC silencing is able to increase IL-8 production and neutrophil activation in pancreatic cancer cells, showing the important role of this mucin in modulating immune response." (PMID 35711414, 2022). "The current review study identifies 22 IHC biomarkers as diagnostic tools for pancreatic cancer that embrace: Pentraxin-3, ENO1, REG4, POSTN, CA125, CA242, Galectin-1, Galectin-9, Maspin, pVHL, MUC1, MUC5AC, THBS2, LTBP2, CPA4, IMP3, CD13, Dkk1, KOC, S100P, Mesothelin, PAM4." (PMID 34988027, 2021). "This study presented a set of glycoproteins having aberrant N-glycosylation levels in pancreatic cancer, including mucin-5AC (MUC5AC), carcinoembryonic antigen-related cell adhesion molecule 5 (CEACAM5), insulin-like growth factor binding protein (IGFBP3), and galectin-3-binding protein (LGALS3BP)." (PMID 33672926, 2021). "In contrast, CDX2 and MUC5AC expression are more common in pancreatic cancer compared with iCCA." (PMID 34201284, 2021). "Healthy pancreas tissue either does not express or weakly expresses mucins, whereas pancreatic cancer is associated with the overexpression of mucins, for example MUC5AC which is uniquely expressed in pancreatic cancer and used as a diagnostic marker." (PMID 32098630, 2020). "Additionally, MUC5AC alone or in combination with CA19–9 emerged as a potential marker to discriminate pancreatic cancer from chronic pancreatitis." (PMID 32098629, 2020). "In addition, MUC5AC enhances pancreatic cancer cell adhesion and invasion potential via up-regulation of integrins, matrix metalloproteinases, and ERK signaling." (PMID 32098629, 2020). "Furthermore, MUC5AC seems to be a sensitive biomarker of early pancreatic neoplasms, providing another link with unfavourable prognosis." (PMID 32745356, 2020). "Genetic and/or epigenetic analysis of the upstream enhancer regions in breast and pancreatic cancers, which were functionally validated in this study, may lead to the understanding of the mechanism by which MUC5AC and/or MUC5B is induced in those cancers." (PMID 28255028, 2017). "They investigated whether the combination of MUC1+cytology and MUC5AC+cytology could provide higher sensitivity and accuracy in a pancreatic cancer diagnosis in comparison with only a cytologic diagnosis." (PMID 23197977, 2012). "In this study, we examined the impact of MUC5AC in a human pancreatic cancer cell line." (PMID 20492722, 2010). "We used two MUC5AC expressing cell lines derived from human pancreatic cancer, SW1990 and BxPC3." (PMID 20492722, 2010). "MUC5AC might contribute to the progression of pancreatic cancer by inducing adhesiveness and invasiveness in ECM via VEGF overexpression, indicating that MUC5AC may be a potentially target in the treatment of pancreatic cancer." (PMID 20492722, 2010). "Our results showed that MUC5AC down regulation suppressed several integrins, MMP-3 and VEGF, indicating that down-regulated MUC5AC in pancreateic cancer might reduce production of VEGF-A resulting in suppression of integrins and MMP-3." (PMID 20492722, 2010). "Notably, one study demonstrated that knocking out the MUC5AC gene in pancreatic cancer cell lines before transplantation into nude mice resulted in significantly reduced tumor weight and fewer metastatic sites, reinforcing its role in tumor progression and metastatic potential." (PMID 40260290, 2025).
pancreatic cancer (continued). "However, MUC5AC expression is found in pancreatic cancer and early pancreatic ductal lesions." (PMID 37241027, 2023). "Interestingly N-glycosilation levels were increased in pancreatic cancer samples,] from proteins such as mucin-5AC (MUC5AC), carcinoembryonic antigen-related cell adhesion molecule 5 (CEACAM5), insulin-like growth factor binding protein 3 (IGFBP3) and galectin-3 binding protein (LGALS3BP)." (PMID 31349663, 2019). "Knockdown of MUC5AC reduced the ability of pancreatic cancer cells to adhesion and invasion, suggesting that MUC5AC might contribute to the invasive motility of pancreatic cancer cells by enhancing the expression of integrins, MMP-3, VEGF and activating Erk pathway." (PMID 20492722, 2010). "Thus, our results suggest that MUC5AC positive pancreatic cancer cells might be activated the invasive potential via VEGFR-1 signaling pathway in an autocrine manner." (PMID 20492722, 2010). "MUC5AC/TFF1 co-expression was particularly common in mucinous carcinoma of the ovary, gastro-intestinal, and bilio-pancreatic neoplasms but also occurred in other entities." (PMID 39410561, 2024). "MUC5AC and CEACAM5 have been shown to play a role in tumor progression and metastasis in pancreatic cancer." (PMID 33672926, 2021). "Serum cancer-specific MUC5AC (NPC-1C antigen) detection by sandwich ELISA colon and pancreatic cancer patients also has reasonable sensitivity and specificity in distinguishing cancer from controls." (PMID 34205412, 2021). "Mucins, especially the highly-glycosylated MUC1, MUC4, MUC5AC, and MUC16, are prominently observed in pancreatic cancer and major carriers of glycans including the CA 19-9 antigen." (PMID 32582529, 2020). "IHC studies conducted on clinical pancreatic tumor specimens confirmed the correlated expression of GLI1 and MUC5AC." (PMID 33266161, 2020). "In BxPC3, the presence of several types of mucins (MUC5AC, MUC5B, and MUC16) reflected what is described for pancreatic tumors, which are known to overexpress these proteins." (PMID 32886718, 2020). "As such, hPAM4 would prevail for MUC5AC with specific decoration, which is mostly produced in PDAC, including the early-stage pancreatic cancer precursors, and occasionally occurs in other epithelial cancers." (PMID 25595893, 2015). "Most pancreatic cancers also express a number of mucins (including MUC1, MUC3, MUC4, MUC5AC), and more recently described markers such as claudin 4 and claudin 18, several S-100 proteins, mesothelin and prostate stem cell antigen." (PMID 22458520, 2012). "Then, to examine the function of MUC5AC in pancreatic cancer cells, we delivered siRNA vector targeting MUC5AC into two human pancreatic cancer cells SW1990 and BxPC3 which were expressed MUC5AC." (PMID 20492722, 2010). "Moreover, stimulation of adenylyl cyclase and the PKA pathway by forskolin and vasoactive intestinal peptide (VIP) increased MUC5AC antigen expression and release from pancreatic cancer cells suggesting that PKA may contribute to the up-regulation of MUC5AC expression seen in PanIN1A." (PMID 24281201, 2010). "The apomucins MUC1, MUC5B, MUC5AC, and MUC6 are expressed in the normal pancreas; MUC1, MUC2, and MUC4 are upregulated in pancreatic tumours, whereas MUC5B, MUC5AC, and MUC6 are slightly downregulated." (PMID 14760381, 2004). "The most common protein carriers of CA19-9 antigen in pancreatic cancer are MUC16, MUC1 and MUC5AC." (PMID 39863644, 2025). "Immunohistochemistry, such as SMAD4, MUC5AC, and CDX2 expression, may be useful to distinguish them; SMAD4 nuclear expression is more preserved in iCCA compared with pancreatic cancer." (PMID 34201284, 2021).
pancreatic cancer (continued). "Moreover, sLex, also called CD15s, is overexpressed on liver acute-phase proteins, including haptoglobin and ceruloplasmin and on mucins MUC1, MUC5AC, and MUC6 in pancreatic cancer." (PMID 33371487, 2020). "Expression of MUC2 mRNA has been correlated with methylation of the proximal region of the promoter in pancreatic cancer cells whereas no direct link was found between methylation and MUC5AC expression." (PMID 24281201, 2010). "MUC5AC protein was detected in 85% of patients with pancreatic cancer, whereas no expression was observed in normal ductal tubular cells." (PMID 20492722, 2010). "Combined detection of biomarkers such as MUC5AC and DUPAN-2 can improve the limitations of false negatives of CA19–9 in Lewis-negative individuals, while the combined detection of CEA and CA125 aids in the differential diagnosis of pancreatic cancer and other gastrointestinal tumors." (PMID 41142819, 2025). "For example, MUC1 and MUC5AC affect E‐cadherin and β‐catenin complexes, thereby promoting the proliferation, invasion, and metastasis of ovarian and gastric cancer cells; in contrast, MUC4 gene deletion in pancreatic cancer cells inhibits tumor progression by regulating apoptosis and cell cycle." (PMID 37666495, 2024). "Prior studies did not clearly establish the role of both kinds of MUC5AC in pancreatic cancer." (PMID 37835525, 2023). "Furthermore, we confirmed that GCNT3 expression correlates with MUC1 and MUC5AC expression (Pearsons’ coefficient (Cor) 0,48 and 0,51 respectively) and that they were all biomarkers of worse prognosis in pancreatic cancer patients (GCNT3, HR = 1.64), (MUC1, HR = 2.56), (MUC5AC, HR = 2.04)." (PMID 37996891, 2023). "Given a positivity rate of >60% in pancreatic cancer and a complete absence of MUC5AC in normal pancreatic tissue, MUC5AC IHC may be most useful for supporting a diagnosis of pancreatic cancer." (PMID 34547930, 2021). "There is preliminary evidence that MUC5AC is immunogenic, and the cytotoxic T lymphocytes (CTLs) are stimulated by it (peptides such as MUC5AC-A02-1398 [FLNDAGACV] and MUC5AC-A24-716 [TCQPTCRSL]) can kill the pancreatic tumor cells and have the potential to be harnessed for vaccine development." (PMID 34205412, 2021). "In our study, proliferation rate was not affected, although invasive and adhesive activities of SW1990 after MUC5AC inhibition were decreased markedly, suggesting that MUC5AC, similarly to MUC1 or MUC4, might have potential to accelerate progression of pancreatic cancer." (PMID 20492722, 2010). "For example, it was shown that CA19-9 expression in MUC5AC and MUC1 proteins may be increased, independently of protein elevation, and that the combined measurement of MUC5AC and CA19-9 presents better performance and improved specificity to differentiate pancreatic cancer subjects from controls." (PMID 37455827, 2023).
gastric cancer (53 papers, 2004 to 2025). A primary or metastatic malignant neoplasm involving the stomach. "A meta-analysis found that during gastric cancer, decreased expression of the pit cell mucin MUC5Ac was associated with deeper tumor penetration and worse overall survival." (PMID 37674528, 2023). "Apparently, MUC5AC has a prognostic value for gastric cancer patients, being positively associated with the disease-free survival period." (PMID 33322136, 2020). "Decreased Muc5AC expression was associated with poor prognosis in gastric cancer, especially advanced gastric cancers." (PMID 28938681, 2017). "There have been many previous reports investigating the expression of MUC5AC and prognosis of gastric cancer, but the association between expression of MUC5AC and malignant potential of gastric cancer is still controversial." (PMID 25166306, 2014). "In gastric cancer, alterations in mucin polypeptide have been reported: loss of expression of MUC5AC, increased mucin heterogenesity." (PMID 16545139, 2006). "Association of MUC5AC-u repetitive region genotypes and gastric cancer risk." (PMID 24887023, 2014). "Functional genetic polymorphisms in the regulation region may affect MUC5AC gene expression and then contribute to an individuals' susceptibility to gastric cancer." (PMID 24887023, 2014). "The increased expression of MUC5AC in pancreatic and lung cancer is correlated with poor prognosis, while in gastric carcinoma, decreased MUC5AC expression correlates with poor prognosis." (PMID 40699805, 2025). "MUC1 and MUC5AC can enhance the proliferative, invasive, and metastatic properties of ovarian and gastric cancers by regulating the E‐cadherin and β‐catenin." (PMID 37666495, 2024). "MUC5AC stains positive in normal gastric foveolar epithelium and gastric cancers, and MUC6 shows positive staining in normal pyloric glands of the stomach and also gastric cancers." (PMID 36001283, 2023). "For example, in gastric carcinoma, a decrease in MUC5AC expression correlates with poor prognosis, whereas in pancreatic, colon, and lung cancers, an increase in MUC5AC correlates with poor prognosis." (PMID 36980526, 2023). "Gastric cancers with a pure AIG background had higher proportions of MUC5AC positivity (8/8 vs. 2/8, p = 0.0007) and MUC6 positivity (8/8 vs. 2/8, p = 0.0007) than did cancers with H. pylori infection." (PMID 35453635, 2022). "Immunohistochemical staining in the matched cohort showed that AIG-related gastric cancer had higher MUC5AC expression (p = 0.0007) and MUC6 expression (p = 0.0007)." (PMID 35453635, 2022). "Notch3 and Jagged2 were found to contribute to the development and glandular differentiation of gastric cancer, together with MUC5AC." (PMID 28938681, 2017). "Based on these backgrounds, we focused on MUC5AC, which is a well-established gastric marker gene and is often used for the clinical assessment of gastric cancer." (PMID 25166306, 2014). "From these results, we are convinced that it is important to elucidate the regulatory mechanism of MUC5AC gene expression for understanding tumorigenesis of gastric cancer." (PMID 25166306, 2014). "There has been little research on MUC5AC function and the mechanisms underlying its role in GC development, until recently it was reported that silencing MUC5AC, using a small hairpin RNA-containing lentivirus, increased gastric cancer cell invasion and migration in vitro." (PMID 24887023, 2014). "In this study we characterized the expression of the transcription factor SOX2 in gastric cancer and related it with clinicopathological features and differentiation markers namely MUC5AC (gastric marker) and CDX2 and MUC2 (intestinal markers)." (PMID 25300947, 2014). "Our present data further showed that decrease of MUC5AC expression advances in the process of gastric canceration." (PMID 25166306, 2014).
gastric cancer (continued). "In the present study, we further showed that MUC5AC expression is apparently related to the tumor stage: advanced gastric cancers present reduced levels of MUC5AC compared with early gastric cancer." (PMID 25166306, 2014). "MUC5AC is a well-known gastric differentiation marker, which has been frequently used for the classification of stomach cancer." (PMID 25166306, 2014). "MUC5AC, a secreted mucin highly detected in the superficial gastric epithelium, is a well-known gastric marker often used for classification of stomach cancer." (PMID 25166306, 2014). "Among the 36 gastric cancer patients tested, the frequency of cancer-related genome rearrangement in the MUC5AC-u repetitive region was 5.6%." (PMID 24887023, 2014). "ZFHX3 may function as transcriptional regulator and was reported to participate in gastric cancer by regulating MUC5AC promoter." (PMID 30286182, 2018). "In the stomach cancers and atrophic gastritis with Helicobacter pylori infection, it has been reported that SOX2 as a SRY-related HMG box protein and AT motif-binding factor 1 (ATBF-1) are associated with the regulation of MUC5AC expression." (PMID 24829572, 2014). "Finally, we confirmed in our TMA that in human subjects with gastric cancer, pit cells (expressing MUC5Ac) could express MUC4." (PMID 37674528, 2023). "MUC5AC was deemed to be involved in gastric carcinogenesis since aberrant MUC5AC expression has been repeatedly detected in patients with gastric cancer (GC)." (PMID 24887023, 2014). "The gastric cancer markers CK7 (-), TTF-1 (-), and NapsinA (-) completely exclude lung derived metastasis, while Muc-2 (+), Muc-5AC (+), and Muc-6 (+) are gastric mucinous phenotypes, indicating gastric primordia." (PMID 40837582, 2025). "The two carbohydrate antigens (CAs), MUC5AC and carcinoembryonic antigen (CEA), are more frequently detected in esophageal than in gastric cancers, according to both immunohistochemical and biochemical data." (PMID 40699805, 2025). "Reduced expression of MUC5AC and MUC6 has been reported as a potential predictor of poor prognosis in gastric cancer.17,18) Consistent with these evidence, the present case showed high malignant potential, with multiple recurrences." (PMID 40589560, 2025). "The expression of MUC5AC, MUC6, MUC2, and CD10 was shown in 346 (52.7%), 425 (64.7%), 149 (22.7%), and 176 (26.8%) of the 657 early differentiated gastric cancer lesions, respectively." (PMID 36977979, 2023). "MUC2 expression decreases during metaplasia from normal gastric mucosa to intestinal-type, whereas MUC5AC is upregulated with more aggressive gastric tumours, and MUC6 is downregulated in gastric cancer." (PMID 37958425, 2023). "AIG-related gastric cancer patients had higher levels of MUC6 and MUC5AC expression in the gastric glands." (PMID 35453635, 2022). "This article reviews the diagnostic and prognostic values of molecular markers in complete (MUC2) and incomplete (MUC2, MUC5AC, and MUC6) intestinal metaplasia, gastric dysplasia/intra-epithelial neoplasia, and early gastric cancer." (PMID 34206291, 2021). "In the human gastric cancer cells, overexpression of Math1 strongly enhanced both the MUC6 and MUC5AC mRNA transcript levels and knockdown of the Hath1 gene significantly decreased the expression of both mucin genes." (PMID 22518155, 2012). "The decreased expression of MUC5AC and MUC6 mucin in gastric carcinomas were confirmed in the present study." (PMID 16545139, 2006). "Studies conducted on gastric cancer cells showed that MUC5AC expression is significantly lower in gastric cancer than in H. pylori negative patients and is higher in the well differentiated forms than in less differentiated forms." (PMID 33322136, 2020). "Contrastively, ATBF1 is negatively regulate MUC5AC expression in human gastric cancer cells, In spite of these results, molecular mechanisms of MUC5AC expression in human gastrointestinal cells have not been fully elucidated." (PMID 25166306, 2014).
gastric cancer (continued). "It was reported that HP infection upregulates MUC2, MUC5AC and MUC6 genes in KATO-III, a cultured gastric cancer cell line; however, it was demonstrated that HP infection reduced the rate of mucin turnover and decreased the levels of Muc1 in the gastric mucosa of mice." (PMID 24810688, 2014). "In gastric cancer (GC), intestinal metaplasia (IM) is a common precursor lesion, but its relationship to the MUC2/MUC5AC/CDX2 axis is not completely understood." (PMID 37240039, 2023). "It indicated that H. pylori urease may downregulate MUC5AC expression in already transformed gastric cancer cells although this phenomenon does not have to refer to primary cells, which may possess diferent mechanisms." (PMID 30841890, 2019). "In most cases, gastric MUC5AC is reduced or absent, while CEA usually demonstrates a higher positivity in esophageal cancer than in gastric cancer." (PMID 40699805, 2025). "Immunohistochemistry revealed that MUC5AC and MUC6 were negative in primary gastric cancer, lymph node metastases, and gallbladder lesions." (PMID 40589560, 2025). "The gastric carcinoma markers MUC2, MUC5AC, and MUC6 were expressed weakly or not at all." (PMID 31367188, 2019).